EGILA (EGFR interacting lncRNA)
Synonyms: Lnc-EGFR
Gene: Long non-coding RNA gene on chromosome 14 (20,693,480 to 20,707,120, reverse strand). Ensembl gene ENSG00000258451.
Diseases named in the same sentence as EGILA in open-access papers:
EGILA is named in the same sentence as 1 disease in open-access papers, as found by Europe PMC text mining. Sharing a sentence is not in itself a finding about the gene and the disease.
EGILA shares sentences with these, for which no sentence is quoted: cancer (1 paper).